IL6 (interleukin 6)
Diseases named in the same sentence as IL6 in open-access papers (continued):
Sharing a sentence is not in itself a finding about the gene and the disease.
Insulin resistance (continued). "At baseline and post-intervention, anthropometrics, body composition, systemic inflammation (high-sensitivity C-reactive protein, tumor necrosis factor-α, and interleukin 6), fasting glucose, insulin and homeostasis model assessment-insulin resistance (HOMA-IR) were determined." (PMID 33126555, 2020). "It has been reported that the initiating factor of insulin resistance may be chronic inflammation, and it has been speculated that IL-6 may be involved in the occurrence of GDM." (PMID 32280713, 2020). "The correlation between the leptin-to-adiponectin ratio and the anthropometric measurements, atherogenic index of plasma, lipid accumulation product, homeostatic model assessment of insulin resistance, interleukin 6, and high-sensitivity C-reactive protein was determined." (PMID 30457109, 2019). "From the data obtained, an improved glucose utilization and AMPK phosphorylation and decreased Akt phosphorylation, suppressor of cytokine signaling 3 (SOCS-3) expression and janus kinase (JAK) expression ultimately resulting in the suppression of IL-6-induced insulin resistance was observed." (PMID 31718066, 2019). "While the IL-6 cytokine can activate an inflammatory response, increase fibronectin expression, enhance endothelial permeability, and stimulate proliferation of mesangial cells, it is also directly involved in the pathogenesis of insulin resistance." (PMID 31886287, 2019). "Secretion of adipokines, such as leptin, adiponectin, and interleukin 6 from these fat depots might result in metabolic dysfunction including insulin resistance." (PMID 31289463, 2019). "Considered as an adipokine, IL-6 is also a multifaceted, pleiotropic cytokine and suggested to play a central role in the development of metabolic syndrome by inducing metaflammation and insulin resistance." (PMID 30697360, 2019). "IL-6, on the other hand, is not only accountable for the sustained inflammatory phenotype of the wound, but also the pathogenesis of type II diabetes, as increased IL-6 plays a role in insulin resistance." (PMID 31626638, 2019). "We also observed increased plasma levels of IL10, which has been shown to inhibit the effects of IL6 with regards to insulin resistance, and may have contributed to the improved insulin sensitivity." (PMID 31724300, 2019). "Finally, we focus on the consequences of inflammatory responses, in particular, the effect of TNF-α, IL-1β and IL-6 on insulin resistance." (PMID 31363792, 2019). "However, reduced insulin resistance, caused by reducing the expression of tumor necrosis factor (TNF)-α and interleukin (IL)-6 and inhibited M1 pro-inflammatory macrophage infiltration in adipose tissue, was suggested as a potential mechanism." (PMID 30735525, 2019). "Preoperative carbohydrate treatment has been reported to reduce insulin resistance, decrease circulating IL-6 concentrations, improve patient well-being, maintain postoperative whole-body protein balance and muscle strength, and result in a shorter hospital stay." (PMID 31092210, 2019). "It is well-known that FFA activates the proinflammatory NF-κB pathway in skeletal muscle and increases the expression of several cytokines including TNF-α, IL-1β, and IL-6 in liver, resulting in insulin resistance including activation of c-Jun NH2-terminal kinase (JNK)." (PMID 31447776, 2019). "Adipose tissue and blood samples were obtained for the analysis of cytokines, Th17 and Treg markers, and insulin sensitivity blood parameters, for comparisons with those of the normal control group, IL-6-blocked control group, and insulin resistance control group." (PMID 31218568, 2019). "The lower IL-6 recorded in happier individuals with diabetes might contribute to reduced progression of diabetes in processes such as insulin resistance and dyslipidemia." (PMID 29924291, 2019). "Studies have confirmed that IL-6 was closely related to type 2 diabetes and insulin resistance." (PMID 30463907, 2019).
Insulin resistance (continued). "Other cytokines, such as TNF-α and IL-6, are also related to insulin resistance." (PMID 31030467, 2019). "It is possible that adherence to an unhealthy plant-based diet could have a particularly strong detrimental effect on IL-6, a marker of inflammation and insulin resistance." (PMID 30927000, 2019). "The inhibition of TNF-α and IL-6 production may be one of the options for preventing the development of insulin resistance and the pathogenesis of T2DM." (PMID 30871060, 2019). "TNF and IL-6 could impair intracellular insulin signalling, potentially leading to insulin resistance." (PMID 31387569, 2019). "The aim of our study was to assay circulating IL-15 and IL-6 levels in patients with newly diagnosed AD, their first-degree relatives, and healthy controls in comparison with the presence of anti-islet antibodies and insulin resistance." (PMID 31772933, 2019). "Statins can reduce levels of CRP and IL-6, and improve insulin resistance." (PMID 31439071, 2019). "Interleukin-6 is a cytokine secreted by adipose tissue being involved in signaling pathways of inflammation and insulin signaling in various tissues and cell types and high circulatory level had been correlated with insulin resistance and type 2 diabetes." (PMID 30605486, 2019). "In fact, modulation of the IL-6/STAT3 hepatic signaling pathway has been proposed as the underlying mechanism accounting for the beneficial effects of Pu-erh tea extract on HFD-induced NASH and insulin resistance." (PMID 30818779, 2019). "IL-6 promotes inflammation and can induce insulin resistance." (PMID 31275749, 2019). "IL-6 affects glucose metabolism and increased circulatory levels of IL-6 in obese and/or T2D patients have been documented; however, its role in the development of insulin resistance remains controversial." (PMID 31718015, 2019). "TNF-α and IL-6 are correlated with insulin resistance, impaired glucose tolerance, and type 2 DM." (PMID 30915195, 2019). "However, the completely opposite effects for all parameters were detected in the insulin resistance IL-6-blocked group." (PMID 31218568, 2019). "As we know, visfatin stimulates the synthesis of TNF and IL-6, which could suggest its adverse effect on the development of insulin resistance." (PMID 29516012, 2018). "IL-6 is a central player in the regulation of inflammation, leading to insulin resistance." (PMID 29849618, 2018). "Among subjects without insulin resistance there was a positive association between stearic fatty acid and IL-6 (p = 0.032), and a negative association between alpha-linolenic fatty acid and pro-inflammatory biomarkers (p < 0.05)." (PMID 29466985, 2018). "Previous studies have demonstrated that STAT3 absence in hepatocytes may result in insulin resistance and augmented expression of gluconeogenic genes, mediated by the dysregulation of IL-6 signaling." (PMID 30205811, 2018). "Second, ferritin, which is an inflammatory factor, has been associated with the tumor necrosis factor-α (TNF-α) and interleukin-6 (IL-6), while elevated TNF-α and IL-6 may contribute to insulin resistance." (PMID 29949646, 2018). "Specific cytokines produced by visceral adipose tissue, such as leptin, adiponectin and inflammatory factors including TNF-α and IL-6, might lead to insulin resistance." (PMID 29965999, 2018). "Obesity, particularly visceral, is strongly associated with dysregulated expression of inflammatory cytokines such as tumor necrosis factor-alpha (TNF-α), interleukin-1 beta (IL-1β), and IL-6, as well as adiponectin and leptin, contributing to metabolic derangement and insulin resistance." (PMID 29910818, 2018). "Our data, in accordance with previous studies, suggests that increased hepatic IL-6 production plays an important role in steatofibrosis, as well as in systemic insulin resistance since adipose tissue-derived IL-6 has been shown to regulate hepatic insulin resistance." (PMID 30024933, 2018).
Insulin resistance (continued). "In keeping with this, a significant correlation between insulin resistance and plasma concentrations of IL-6 has been reported in patients undergoing open cholecystectomy and hernia repair, with only minor increments in the levels of stress hormones postoperatively." (PMID 29129636, 2018). "Higher overall adiposity levels are associated with increased IL-6, TNF-α, and leptin expression, and lower adiponectin expression, which all could promote an insulin resistance state." (PMID 29867770, 2018). "Ultimately, we note that individuals with lipodystrophy have an increase in serum interleukins, keys of the inflammatory process, as IL-1β, TNF-α and IL-6 (p < 0.05 all), compared with healthy individuals, which can be the trigger to insulin resistance in this population." (PMID 29449893, 2018). "They concluded that IL-6 might be involved in the development of both increased blood glucose and insulin resistance." (PMID 30914847, 2018). "These multiple effects of IL-6 on metabolism lead to hyperglycemia and insulin resistance." (PMID 30584465, 2018). "Furthermore, it has been established that inflammatory cytokines TNF-α and IL-6 inhibit the expression of insulin signaling mediators in adipose tissue leading to a worsening of whole-body insulin resistance and glucose intolerance." (PMID 30510798, 2018). "The binding of LPS with TLR4 could result in the stimulation of IKKβ and NF-κB and then increase the levels of downstream inflammatory factors (like TNF-α, IL-6, IL-1β, etc.), which promoted the insulin resistance in the tissue where they were produced." (PMID 30210342, 2018). "Inflammatory cytokines IL-6 and TNF-α have been implicated in insulin resistance." (PMID 30526660, 2018). "The increases in monocyte TLR4 and phosphorylated JNK and p38 levels caused by lipid infusion were associated with enhanced production of multiple cytokines, including IL-1β, IL-6, MCP-1, and TNFα, all of which have been implicated in insulin resistance and type 2 diabetes." (PMID 29649324, 2018). "Importantly, IL-6-mediated lipolysis and induction of systemic insulin resistance in HFD-fed mice require ATX and LPA1/3, since administration of Ki16425 for one week decreased plasma free fatty acids and improved glucose homeostasis." (PMID 29570618, 2018). "However, few studies have investigated the effect of long-term treatment of IL-6, leading to glucose intolerance and insulin resistance." (PMID 28706484, 2017). "Increases in the levels of pro-inflammatory cytokines, such as interleukin-6 (IL-6) and tumor necrosis factor α (TNF-α), are observed in individuals with insulin-resistance, which may induce bone loss by stimulating osteoclast activity." (PMID 28704413, 2017). "Under specific conditions, IL-6 may either decrease or enhance insulin resistance, as well as improve glucagon-like peptide-1-mediated insulin section." (PMID 29163354, 2017). "In addition, hepatic inflammation and fibrosis are also linked to adipose inflammation and insulin resistance, through a release of inflammatory mediators such as TNF-α, IL-6, and monocyte chemoattractant protein-1 (MCP-1) from adipose tissue." (PMID 28759632, 2017). "Wunderlich and colleagues have shown that IL-6 action, which originates from the activation of Kupffer cells in the liver, leads to a restricted inflammation, not only locally but also systemically, and therefore prevents insulin resistance." (PMID 28299341, 2017). "Increases in IL-1β, IL-6, and TNF-α are associated with insulin resistance and glucose intolerance." (PMID 28420148, 2017). "As there is a significant association between β-cell damage and inflammation, this study sought to assess the host circulating levels of pro-inflammatory cytokines TNF-α and IL-6 as they are known to play an important role in the pathogenesis/progression of insulin resistance." (PMID 28077129, 2017).
Insulin resistance (continued). "The action of IL-6 may be considered a “two-way street,” since high levels of IL-6 may be regarded as an insulin resistance predictor of endothelial function and hence may be involved in the development of type 2 diabetes." (PMID 28878683, 2017). "Furthermore, M1 macrophages secrete pro-inflammatory cytokines including TNFα, IL-1β, and IL-6, some of which can directly alter insulin receptor signaling in adipocytes, leading to insulin resistance." (PMID 29163218, 2017). "Finally, adipocyte-derived IL-6 is related to the occurrence of insulin resistance and metabolic disorder." (PMID 28025491, 2016). "Recent attention has been directed towards the divergent results of vitamin D between prospective studies and randomized trials; indeed, this systematic review also shows inconsistencies for markers of inflammation (i.e. CRP, IL-6), glucose measures and insulin resistance (i.e. HbA1c, HOMA-IR)." (PMID 27116227, 2016). "OPN, IL‐6 and CCL‐2 have all been implicated in insulin resistance." (PMID 27135421, 2016). "Interestingly enough, these cytokines have been implicated in insulin resistance (TNF-α, IL-6, and IL-1β), atherosclerotic plaque destabilization (IL-18), and future cardiovascular events (IL-6, IL-18, IL-1β, and TNF-α)." (PMID 27034691, 2016). "Additionally, TNF-α and IL-6 are strong mediators of insulin resistance, which is the best-examined link in the pathogenesis of polycystic ovarian syndrome." (PMID 26942201, 2016). "IL-6 is one of the most studied inflammatory cytokine, which modulates insulin resistance via numerous mechanisms such as the c-Jun N-terminal kinase 1 (JNK1)-mediated serine phosphorylation of IRS1, with elevated circulating IL-6 levels observed in insulin-resistant subjects." (PMID 26842399, 2016). "Studies have highlighted the fact that insulin resistance is a characteristic feature of NAFLD and is caused by a variety of factors, including soluble mediators derived from immune cells and/or adipose tissue, such as TNF-α and IL-6." (PMID 27247565, 2016). "Previous studies indicated that miR-200s participated in IL-6-induced hepatic insulin resistance." (PMID 27166182, 2016). "Besides, these two pathological situations are marked with high concentrations of inflammatory mediators like tumor necrosis factor-α (TNF-α) and interleukin-6 (IL-6), known to play a pivotal role in insulin resistance." (PMID 27313878, 2016). "IL-6 is another factor that might be closely related to adipose inflammation and insulin resistance." (PMID 26901838, 2016). "However, once insulin resistance arises, the inflammatory pathways are activated, and the levels of IL-6, IL-8, TNF-α, and CRP increase significantly and produce different degrees of injury in the body." (PMID 27187341, 2016). "The host immune response to H. pylori infection is complex and involves up regulation of several pro-inflammatory cytokines, such as C-reactive protein (CRP), interleukin 6 (IL-6), and tumor necrosis factor- α (TNF-α), which are implicated in insulin resistance and the development of diabetes." (PMID 27148410, 2016). "Several cross-sectional studies showed that insulin resistance and type 2 diabetes are associated with higher levels of C-reactive protein (CRP), interleukin-6 (IL-6), interleukin-1β, and tumor necrosis factor-α (TNF-α), which are markers of subclinical systemic inflammation." (PMID 27034691, 2016). "CCL2 recruits macrophages to the adipose tissue, resulting in even more local cytokine production and perpetuating the inflammatory cycle; TNF-α and IL-6 induce a state of insulin resistance in adipocytes, which stimulates triglyceride lipolysis and fatty acid release into the circulation." (PMID 27247565, 2016). "In addition, IL-6 induces the downstream NF-κB signaling pathway which impairs insulin signaling and subsequently induces insulin resistance in insulin-dependent tissues of obese humans and animals." (PMID 27069930, 2016).
Insulin resistance (continued). "PGRN seems to promote interleukin-6 (IL-6) expression, leading to insulin resistance." (PMID 27776152, 2016). "In the pSoBid cohort, we have demonstrated previously that lower socio-economic status is associated with the expression level of the pro-inflammatory cytokine Interleukin 6 (IL-6), a marker of cardiovascular disease and with features of insulin resistance, such as elevated adipokine levels." (PMID 27132985, 2016). "Atorvastatin treatment improves insulin resistance which may be related to its positive impact on Il6 and Slc2a4/GLUT4 expression in SAT." (PMID 25834641, 2015). "Interestingly, pro-inflammatory cytokines such as TNF-α and IL-6, key players of the TLR4 signaling pathways, have also been implicated in the pathogenesis of impaired glucose uptake and insulin resistance in humans and rodents." (PMID 26539824, 2015). "They showed that PGRN expression was induced by TNF-α or dexamethasone and decreased with differentiation of adipocytes, and ablation of PGRN prevented mice from high fat diet-induced insulin resistance and blocked elevation of an inflammatory cytokine, IL-6, in adipose tissue." (PMID 26106251, 2015). "In addition insulin resistance was associated with circulating levels of TNF-α (T = 2.76, p = 0.009) and circulating levels of IL-6 (T = 2.81, p = 0.008)." (PMID 26061745, 2015). "Glucose uptake and consumption were improved in the rapamycin plus TNF-α or IL-6 groups compared with cells treated with TNF-α or IL-6 alone in the absence and presence of insulin, suggesting that rapamycin ameliorates inflammatory stress-induced insulin resistance in vitro." (PMID 26449763, 2015). "Studies indicating that IL–6 is associated with insulin resistance are challenged by several findings showing that IL–6 actually has insulin-sensitizing effects and that blocking of IL–6 may induce insulin resistance." (PMID 26448147, 2015). "In addition to leptin an ever expanding number of adipokines are produced by the adipose tissue eg TNF-α, and IL-6 are known to promote insulin resistance which was corroborated here." (PMID 26061745, 2015). "However, a clear conclusion about causality cannot be obtained from the present study and the role of IL-6 in T2D and in insulin resistance remains debatable." (PMID 25763111, 2015). "Similarly, inflammatory markers, such as TNF-α, IL-6, and FFA, which are the root causes of insulin resistance in diabetic patients, were greatly increased in control group, compared with the normal group." (PMID 25889508, 2015). "IL-6 is another important cytokine involved in the regulation of insulin resistance." (PMID 26077338, 2015). "Moreover, increased activation of inflammatory pathways (i.e., p38 MAPK and NF-κB) in presence of insulin resistance is evidenced together with elevated protein mass of IL-6, ICAM and COX-2, as well as of the mRNA levels of TNF-α." (PMID 26376914, 2015). "IL-6 promotes insulin resistance by activating the STAT3–SOCS3 pathway in the liver." (PMID 26077338, 2015). "Cytokines, as IL-6 and TNF-alpha, are elevated in diabetic patients, suggesting that the pattern of circulating inflammatory cytokines modifies the risk for diabetes and is correlated with insulin resistance." (PMID 25922592, 2015). "Also, IL-6 mediates, at least in part, hepatic insulin resistance due to impairment of insulin receptor and IRS-1 phosphorylation." (PMID 26578976, 2015). "One possibility may be via the association between insulin resistance and WBC; another one, via proinflammatory cytokines, like TNF-α and IL-6 released from adipose cells, that elevate the WBC count." (PMID 26180744, 2015). "Although type 2 DM is associated with IL-6 polymorphism and higher plasma concentrations of IL-6, there is no direct evidence for an association between IL-6 expression and pregnancy-induced insulin resistance." (PMID 25202741, 2014).